PTPRN2 (protein tyrosine phosphatase receptor type N2)
Description:
Plays a role in vesicle-mediated secretory processes. Required for normal accumulation of secretory vesicles in hippocampus, pituitary and pancreatic islets. Required for the accumulation of normal levels of insulin-containing vesicles and preventing their degradation. Plays a role in insulin secretion in response to glucose stimuli. Required for normal accumulation of the neurotransmitters norepinephrine, dopamine and serotonin in the brain. In females, but not in males, required for normal accumulation and secretion of pituitary hormones, such as luteinizing hormone (LH) and follicle-stimulating hormone (FSH) (By similarity). Required to maintain normal levels of renin expression and renin release (By similarity). May regulate catalytic active protein-tyrosine phosphatases such as PTPRA through dimerization (By similarity). Has phosphatidylinositol phosphatase activity; the PIPase activity is involved in its ability to regulate insulin secretion. Can dephosphorylate phosphatidylinositol 4,5-biphosphate (PI(4,5)P2), phosphatidylinositol 5-phosphate and phosphatidylinositol 3-phosphate (By similarity). Regulates PI(4,5)P2 level in the plasma membrane and localization of cofilin at the plasma membrane and thus is indirectly involved in regulation of actin dynamics related to cell migration and metastasis; upon hydrolysis of PI(4,5)P2 cofilin is released from the plasma membrane and acts in the cytoplasm in severing F-actin filaments.
Synonyms: R-PTP-N2; IAR; ICAAR; KIAA0387; phogrin; IA-2beta; PTPRP
Tractability: Antibody: its Gene Ontology location is reachable by antibodies, with high confidence; UniProt predicts a signal peptide or a membrane-spanning region. PROTAC: its protein half-life has been measured.
Gene: Protein-coding gene on chromosome 7 (157,539,056 to 158,587,823, reverse strand). Ensembl gene ENSG00000155093.
Subcellular location: Cytoplasmic vesicle, secretory vesicle membrane; Cytoplasmic vesicle, secretory vesicle, synaptic vesicle membrane; Cytoplasmic vesicle, secretory vesicle membrane (IA-2beta60)
Subcellular location (Human Protein Atlas): Vesicles
Pathways (Reactome):
Immune System: Neutrophil degranulation
Gene Ontology:
Molecular function: transmembrane receptor protein tyrosine phosphatase activity; protein tyrosine phosphatase activity
Biological process: insulin secretion involved in cellular response to glucose stimulus; neurotransmitter secretion; protein dephosphorylation; regulation of secretion
Cellular component: receptor complex; ficolin-1-rich granule membrane; plasma membrane; secretory granule; secretory granule membrane; synapse; synaptic vesicle membrane; transport vesicle membrane
Genetic constraint (gnomAD): Loss-of-function variants: 68 observed, 102.6 expected, observed/expected ratio (o/e) 0.66, 90% interval 0.54 to 0.81. The upper end of that interval is the gene's LOEUF score, 0.81, which puts it in group 3 of 6, group 1 being the genes least tolerant of losing a copy. Missense variants: 1,459 observed, 1,285.8 expected, observed/expected ratio (o/e) 1.13, 90% interval 1.09 to 1.18. Synonymous variants: 632 observed, 569.25 expected, observed/expected ratio (o/e) 1.11, 90% interval 1.04 to 1.19.
Homologues: Orthologues: macaque PTPRN2 (95% identical), rat Ptprn2 (71% identical), mouse Ptprn2 (70% identical), pig PTPRN2 (63% identical), tropical clawed frog ptprn2 (55% identical), zebrafish ptprn2 (46% identical). Paralogues in human: PTPRN (40% identical), PTPRF (19% identical), PTPRD (19% identical), PTPRS (18% identical), PTPRB (18% identical), PTPN13 (16% identical), PTPRZ1 (16% identical), PTPRT (16% identical), PTPRK (16% identical), PTPRM (15% identical), PTPRG (15% identical), PTPN23 (15% identical), and 23 more.
Diseases named in the same sentence as PTPRN2 in open-access papers:
PTPRN2 is named in the same sentence as 96 diseases in open-access papers, as found by Europe PMC text mining. Sharing a sentence is not in itself a finding about the gene and the disease. The quoted sentences say what the papers report.
type 1 diabetes (30 papers, 2008 to 2024). "PTPRN2 encodes a major islet autoantigen in type 1 diabetes and is involved in the regulation of obesity mechanisms." (PMID 38336605, 2024). "PTPRN2 encodes the protein tyrosine phosphatase receptor type N2 (IA-2β), which is a major autoantigen in Type 1 diabetes and is expressed on dense core and synaptic vesicles." (PMID 39070644, 2024). "A significant islet autoantigen for type 1 diabetes is encoded by PTPRN2 (protein tyrosine phosphatase, receptor type N2)." (PMID 37239458, 2023). "A major autoantigen associated with insulin-dependent diabetes mellitus, PTPRN2 (protein tyrosine phosphatase), was identified for the 16 mostly hypomethylated CpG loci." (PMID 35163587, 2022). "PTPRN2 (protein tyrosine phosphatase, receptor type, N polypeptide 2) encodes a major autoantigen of relevance to type 1 diabetes." (PMID 31999706, 2020). "Protein tyrosine phosphatase, receptor type N2 (PTPRN2) encodes a major islet autoantigen in type-1 diabetes." (PMID 30890718, 2019). "Protein encoded by PTPRN2 (also known as IAR) is a known autoantigen in insulin-dependent diabetes mellitus." (PMID 28558807, 2017). "PTPRN2 protein was identified as a major autoantigen associated with insulin-dependent diabetes mellitus." (PMID 25958397, 2015). "Finally, PTPRN2 encodes islet antigen (IA)-2β which, together with IA-2, functions as an autoantigen associated with type 1 diabetes mellitus (T1DM)." (PMID 35806113, 2022). "PTPRN2 encodes a protein that functions as a major islet auto-antigen in type I diabetes." (PMID 35500004, 2022). "Following up on the diabetes link mentioned just above, the simple tandem repeat sequences (STRs) in PTPRN2 are viewed as a source for somatic mutations that could trigger an autoimmune response as in type 1 diabetes." (PMID 36755664, 2022). "PTPRN2 as a major autoantigen in insulin-dependent diabetes mellitus may explain its genetic and epigenetic associations with FPG." (PMID 30890718, 2019). "Interestingly, the PTPRN2 gene encodes a protein that is an autoantigen in type 1 diabetes." (PMID 25375650, 2014). "PTPRN2 is an autoantigen in insulin-dependent diabetes and has been mainly studies in relation to metabolic diseases such as obesity, diabetes, and cancer." (PMID 38212800, 2024). "At the same time, LTR69_Dup69 is located within an intron of the PTPRN2 gene, which is also up-regulated upon SARS-CoV-2 infection and encodes for an autoantigen involved in type 1 diabetes." (PMID 37667401, 2023). "PTPRN2, annotated to 16 mostly hypomethylated DML, encodes the tyrosine phosphatase, a major islet autoantigen in type-1 diabetes." (PMID 35163587, 2022). "The most important beta cell autoantigens in type 1 diabetes (Ins1/2, Slc30a8, Ica1, Gad1, Ptprn2) were expressed at higher levels in Zbed6-KO islets." (PMID 34296320, 2021). "Receptor-type tyrosine-protein phosphatase N2 (PTPRN2) was shown to act as an autoantigen in type I diabetes and be required for the accumulation of insulin-containing vesicles, preventing their degradation in rat gastrointestinal endocrine cells." (PMID 32316277, 2020). "Of note, PTPRN2 has been shown to be a target of autoantibodies in Type I diabetics and a regulator of insulin secretion." (PMID 32291385, 2020). "LAT as a gene involved in KEGG immune and inflammatory pathways, whereas PTPRN2 and PDE9A were previously shown to be associated with type I diabetes mellitus pathway and purine metabolism, respectively." (PMID 31221986, 2019). "The two most significant DMPs were found in PTPRN2 and BCL11A, with the former being associated to type 1 diabetes in mice and the latter to type 2 diabetes in human males." (PMID 27279921, 2016). "TPO encodes a primary autoantigen in both Hashimoto's Thyroiditis (HT) and Graves' Disease (GD); PTPRN2, and FLG encode primary autoantigens in Type-1 Diabetes (T1D) and Rheumatoid Arthritis (RA) respectively." (PMID 24988487, 2014).
type 1 diabetes (continued). "Protein tyrosine phosphatase, receptor type, N polypeptide 2 (PTPRN2) is an autoantigen involved in insulin dependent diabetes mellitus." (PMID 18616821, 2008). "Finally, our enrichment analysis identified within our DMPs, relevant pathways related to type I diabetes mellitus (PTPRN2) insulin resistance (RPS6KA2) and secretion (ADCYAP1R1)." (PMID 37415231, 2023). "Moreover, relevant pathways related to type I diabetes mellitus (PTPRN2), insulin resistance (RPS6KA2), and insulin secretion (ADCYAP1R1) were also identified." (PMID 37415231, 2023). "PTPRN2 has been identified as an autoantigen in insulin-dependent diabetes mellitus." (PMID 29423105, 2018). "PTPRN2 has been identified as an autoantigen in type 1 diabetes." (PMID 29228058, 2017). "PTPRN2 is a well-known member of the major auto-antigens in insulin-dependent diabetes mellitus." (PMID 26039411, 2015). "This was also reflected in the KEGG pathway analysis of trans-mQTLs where type 1 diabetes was found to be an enriched pathway of relevance in human pancreatic islets, including the following genes: PTPRN2, HLA-DRB1, HLA-B, HLA-C, HSPD1 and HLA-DRB5 (Padj = 6.0×10−4)." (PMID 25375650, 2014). "PTPRN and PTPRN2 are both expressed in neuro-endocrine cells and proteolytic processing of their products yields protein fragments that represent major autoantigens in type 1 diabetes and are critical regulators of endocrine secretion in adrenal, pancreatic and brain tissue." (PMID 36755664, 2022). "Phogrin (IA-2β or PTPRN2) and IA-2 (PTPRN or ICA512), autoantigens in insulin-dependent diabetes, are type 1 transmembrane proteins belonging to the IA-2 family of protein-tyrosine phosphatase (PTP)." (PMID 38201998, 2024). "Little is known about the function of PTPRN2, a receptor type protein tyrosine phosphatase (PTP) that is a major autoantigen in insulin-dependent diabetes mellitus and that is also expressed in the cerebellum and other parts of the nervous system." (PMID 21731750, 2011). "Methylation of non-REs in PTPRN2 has been associated with HCC risk previously, and it may also be indirectly associated with HCC risk via insulin-dependent diabetes mellitus." (PMID 31639042, 2019).
diabetes (22 papers, 2008 to 2024). "LTR69_Dup69 is located about 500 bp upstream of a long non-coding RNA gene (ENSG00000289418) and within the PTPRN2 gene encoding a diabetes-associated autoantigen." (PMID 37667401, 2023). "Identified as an auto-antigen in diabetes, PTPRN2 has previously been linked to CKD, fasting plasma glucose and obesity." (PMID 33933144, 2021). "Among the highly probable genes involved in the pathogenesis of diabetes in GK rat, it has been demonstrated that the overexpression or inhibition of Fam3b, Ptprn2, Ide, Hnf4g, Bad and Bmp4 is associated with the glucose tolerance in rodents." (PMID 30687391, 2018). "An interaction between C2CD4A or C2CD4B and PTPRN2 in the pituitary (and possibly the beta cell) may, therefore, contribute to the effects of altered expression on diabetes risk." (PMID 33492421, 2021). "However, the genes Bmp4, Fam3b, and Ptprn2 were found to be associated with diabetes in GK rats for the first time in the present study." (PMID 30687391, 2018). "Previous studies have shown that PTPRN2 was a biologically relevant candidate gene for metabolic diseases, such as obesity, diabetes and cancers." (PMID 33242228, 2021). "There are in the human genome 448 genes that contain one or more clusters, and 24 genes that contain more than two clusters, reaching a maximum of nine clusters in the diabetes-related PTPRN2 and the potential tumor suppressor CSMD1." (PMID 33741065, 2021). "Importantly, sQTLs also affected genes that harbor variants that cause monogenic diabetes (KCNK16, ABCC8, PDX1) or influence T2D risk (THADA, PAM) as well as genes that play a role in T1D pathogenesis (ICA1, PTPRN2, HLA-B)." (PMID 36109769, 2022). "Here, we report for the first time that Fam3b, Ptprn2 and Bmp4 are related to diabetes in GK rats." (PMID 30687391, 2018). "It is worth noting that the roles of PTPRN2, ASTN2, GRIN1, SLC6A18, and PDE2A in influencing FPG levels or diabetes had previously been suggested." (PMID 37461060, 2023). "It is intriguing that just like PTPRN2, NEUROD proteins appear to be involved both in diabetes mellitus and cerebellar development." (PMID 21731750, 2011).
breast carcinoma (19 papers, 2009 to 2025). "Overexpression of PTPRN2 is associated with worse overall survival and distal metastasis-free survival in patients with breast cancer." (PMID 34336846, 2021). "PTPRN2 is significantly overexpressed in a subset of tumors, including colon, prostate, pancreas, and breast cancers." (PMID 40424447, 2025). "Downregulation of PTPRN2 in metastatic breast cancer cells inhibited migratory potential and proliferation of xenograft tumors in vivo." (PMID 36650953, 2023). "As a member of the protein tyrosine phosphatase family, PTPRN2 also promoted breast cancer cell migration by regulating actin dynamics through the dephosphorylation of phosphatidylinositol 4,5-bisphosphate." (PMID 34336846, 2021). "A study on metastatic breast cancer cell lines established that PLCβ1 interacts with the Protein Tyrosine Phosphatase Receptor Type N2 (PTPRN2) protein." (PMID 32276377, 2020). "It was reported that PTPRN2 was a novel candidate biomarker and therapeutic target in breast cancer." (PMID 29423105, 2018). "To functionally test their roles in breast cancer metastasis, we depleted PTPRN2 and PLCβ1 in highly metastatic LM2 cells and performed tail vein metastatic colonization assays." (PMID 26620550, 2016). "In contrast, high PTPRN2 expression has been reported to correlate with poor clinical outcomes in breast cancer cases." (PMID 27586084, 2016). "Knockdown of PTPRN2 or PLCβ1 in four other breast cancer cell lines (BT‐549, CNLM1a, HCC‐1806, and MDA‐MB‐468) also significantly reduced the migratory capacity of these cells." (PMID 26620550, 2016). "In the setting of PTPRN2 overexpression, cofilin depletion decreased migration and invasion of breast cancer cells by greater than 70%." (PMID 26620550, 2016). "Overexpression of both PTPRN2 and PLCβ1 further increased the migratory capacity of breast cancer cells to a greater extent than overexpression of either gene alone." (PMID 26620550, 2016). "Both PTPRN2 and PLCβ1 also demonstrated localization to the plasma membrane in breast cancer cells, in addition to some cytoplasmic localization (Fig EV3A)." (PMID 26620550, 2016). "Increased expression of PLCB1 and PTPRN2 correlates with worse overall survival and distal metastasis‐free survival in breast cancer patients, further underscoring the clinical relevance of these findings." (PMID 26620550, 2016). "To investigate the clinical significance of these genes, we quantified the expression levels of PTPRN2 and PLCβ1 in primary tumor cDNA samples derived from patients diagnosed with various stages of breast cancer." (PMID 26620550, 2016). "Furthermore, altered PTPRN2 expression has been connected to breast cancer cell migration via cytoskeleton remodeling." (PMID 37094040, 2023). "In addition, several studies have indicated that PTPRN2 promotes the metastasis of breast cancer cells and that ARMC10 plays a crucial role in mitochondrial dynamics." (PMID 32528873, 2020). "Moreover, PTPRN2 induces metastatic breast cancer cell migration through PI P2‐dependent actin remodeling." (PMID 31221986, 2019). "Loss of PTPRN2 in breast cancer cells promoted apoptosis and blocked tumor formation in mice, whereas enforced expression of PTPRN2 in nontransformed human mammary epithelial cells exerted a converse effect." (PMID 29423105, 2018). "Furthermore, increased expression of both PTPRN2 and PLCB1 associated with significantly worse overall survival and worse distal metastasis‐free survival in two large breast cancer patient cohorts." (PMID 26620550, 2016). "Furthermore, experimental down-regulation of PTPRN2 in metastatic breast cancer cells inhibited migratory potential and yielded smaller tumors in vivo, rather pointing to oncogenic potential." (PMID 27586084, 2016).
breast carcinoma (continued). "Our results do not preclude the possibility of a role for PTPRN2 in constitutive secretion utilized by breast cancer cells, as we observed defects in invasion, a process dependent on secretion of extracellular modifying proteins, upon depletion of PTPRN2 in highly metastatic breast cancer cells." (PMID 26620550, 2016). "In this study, cfDNA mapped to TRAF3IP3, PTPRN2 and GALNT9 gene loci in hypomethylated regions exhibited substantially increased short fragments ratio in patients with breast cancer." (PMID 37740218, 2023). "Survival analysis was performed to explore the correlation between the 4 DEGs (GFRA3, NPY1R, PTPRN2 and GABRP) with patients’ survival in over 400 breast cancer samples from TCGA database." (PMID 29423105, 2018). "To further test the ability of PTPRN2 and PLCβ1 to promote metastasis, we overexpressed these genes in the less metastatic MDA parental breast cancer cells (Fig EV2F and G)." (PMID 26620550, 2016). "For instance, the altered cfDNA fragmentation profile in TRAF3IP3, PTPRN2 and GALNT9 gene loci, along with their upregulated expression could remind us the chromatin changes due to the development of breast carcinomas." (PMID 37740218, 2023). "PTPRN2, MERTK, TNC and SOX4 were identified to be targets of miR-335, AIB1 and CCND1 were the targets of miR-17-5p, and H-RAS and HMGA2 were verified as targets of let-7 in breast cancer." (PMID 30309377, 2018). "Given the changes in cofilin localization and its activity observed upon PLCβ1 and PTPRN2 modulation, we next asked whether these changes in CFL1 localization alter the actin cytoskeleton in breast cancer cells." (PMID 26620550, 2016). "Interestingly, expression levels of PTPRN2 and PLCB1 are significantly positively correlated in primary tumors from a cohort of breast cancer patients." (PMID 26620550, 2016).
Obesity (8 papers, 2018 to 2025). Accumulation of substantial excess body fat. "Differential methylation of the PTPRN2 gene and higher risk of obesity in children, type 2 diabetes, cognitive decline, future cardiovascular risk, and cancer, have been reported in some studies." (PMID 35052758, 2021). "Other studies analyzing methylation patterns between obese and non-obese individuals have shown that genes such as NRF1, ADR1B, and PTPRN2 have differential methylation patterns, highlighting their potential as biomarkers to predict the risk of developing obesity." (PMID 40564006, 2025). "Furthermore, studies examining the methylation patterns of CpG islands in obese versus non-obese individuals have found differential methylation of genes such as NRF1, ADR1B, and PTPRN2, highlighting their potential as biomarkers for obesity risk." (PMID 40564006, 2025). "Methylation loci associated with obesity (AEBP2), calcium signaling (CAPNS1), insulin signaling (INSR, PTPRN2, RPTOR) and vasodilation (VASP) also appeared to be epigenome-wide significant." (PMID 29692868, 2018). "Together with our result, these literatures suggest that the methylation level of PTPRN2 might be on the pathway from maternal BMI to offspring obesity." (PMID 37612641, 2023). "In addition to the findings of these immune-regulatory genes, many other top associations have been implicated in obesity (AEBP2) (FDR < 0.10), calcium signaling (CAPNS1), insulin signaling (INSR, PTPRN2, RPTOR), and vasodilation (VASP)." (PMID 29692868, 2018).